AQP3 (aquaporin 3 (Gill blood group))
Diseases named in the same sentence as AQP3 in open-access papers (continued):
Sharing a sentence is not in itself a finding about the gene and the disease.
gastric cancer (continued). "Similarly in gastric cancer, the water transporting protein aquaporin-3 (AQP3) is an important oncogenic protein which was experimentally validated to be targeted by miR-874." (PMID 24670365, 2014). "We further investigated whether the ERK signaling pathway is involved in H. pylori-regulated AQP3 expression in human gastric cancer." (PMID 23152856, 2012). "We transfected the human gastric cancer cell lines with siRNA against AQP3 or scrambled siRNA." (PMID 23152856, 2012). "Xu and associates investigated the effect of AQP3 on matrix metalloproteinase in human gastric carcinoma cells and concluded that AQP3 may be a promising drug target." (PMID 23043286, 2012). "Our previous studies showed that aquaporin 3 (AQP3) is overexpressed in gastric carcinoma and promotes the migration and proliferation of human gastric carcinoma cells, suggesting that AQP3 may be a potentially important determinant of gastric carcinoma." (PMID 23152856, 2012). "In the present study, we investigated the relationship between the expression of AQP3 in gastric carcinoma tissues or corresponding normal mucosa and H. pylori infection status, and the effects of H. pylori on AQP3 expression in gastric cells were examined in vitro and in vivo." (PMID 23152856, 2012). "Aquaporin-3 (AQP3) also plays a critical role in gastric cancer cell migration and proliferation." (PMID 21943213, 2011). "In conclusion, our findings emphasize that AQP3 might up-regulate MMPs proteins expression via the PI3K/AKT signal pathway in human gastric carcinoma SGC7901 cells." (PMID 21943213, 2011). "Our findings showed that AQP3 might positively regulate MMPs proteins expression through PI3K/AKT signal pathway in human gastric carcinoma SGC7901 cells." (PMID 21943213, 2011). "Likewise, AQP3 was reported to promote EMT through the activation of the PI3K/Akt/SNAIL signaling pathway in gastric cancer cells and was found to contribute to stem-like properties, facilitating tumor growth via the Wnt/glycogen synthase kinase-3 beta (GSK-3β)/β-catenin signaling pathway." (PMID 39941100, 2025). "Indeed, another study has also confirmed that mTOR signaling pathway could regulate AQP3 expression, and overexpression of AQP3 could induce autophagy and promote proliferation and migration of gastric cancer cells." (PMID 38089478, 2023). "Interestingly, AQP3 knockdown inhibits autophagy in gastric cancer cells." (PMID 33917751, 2021). "However, AQP3 appears to be oncogenic in the literature, as knockout makes mice resistant to skin tumor formation and overexpression correlates with metastasis and poor prognosis in the breast or gastric cancer." (PMID 34830961, 2021). "In which, we revealed AQP3, AQP9, and AQP11 mRNA expression were associated with improved OS in all gastric cancer patients especially with intestinal subtypes, whereas AQP0, AQP1, AQP4, AQP5, AQP6/2L AQP8, and AQP10 mRNA expression were associated with poor OS in all gastric cancer patients." (PMID 29678898, 2018). "Moreover, in a recent study, AQP3 has been proposed as a potential biomarker for the diagnosis of gastric intestinal metaplasia, which may finally transform into gastric cancer." (PMID 27589719, 2016). "Furthermore, we showed that upregulation of AQP3 can promote the migration and proliferation of human gastric cancer cells via promoting epithelial-to-mesenchymal transition, indicating that AQP3 plays an important role in gastric cancer carcinogenesis and progression." (PMID 26506416, 2015). "Therefore, further studies that investigate whether H. pylori infection upregulates AQP3 expression in gastric cancer cells via CagA protein during carcinogenesis are warranted." (PMID 23152856, 2012). "Overexpression of AQP3 and AQP5 has been reported in gastric carcinoma, where the level of expression has correlation with metastasis of lymph nodes and lymphatic vascular aggression." (PMID 40100646, 2025).
gastric cancer (continued). "Moreover, Overexpression of AQP3 in gastric cancer cells promotes cisplatin resistance through autophagy, indicating that the invention of AQP3-based tumour treatments might act a significant function in the prospective remedy of gastric cancer." (PMID 38336645, 2024). "AQP3 overexpression increased MMP-3 secretion in prostate cancer cells and MT1-MMP, MMP-2, and MMP-9 in gastric cancer cells." (PMID 37681917, 2023). "In gastric cancer cells (SGC7901), AQP3 levels were correlated with MMP2, MMP9, and MT1-MMP levels, and enhanced invasiveness via phosphoinositide 3-kinase signaling." (PMID 29922644, 2018). "AQP3 knockdown decreased both TCF and LEF expression levels in SGC7901 and MGC803 gastric cancer cells." (PMID 28991174, 2017). "Together, our data demonstrate that AQP3 facilitates cisplatin resistance in gastric cancer cells via autophagy, and suggest that the development of AQP3-based tumor therapeutics could play a key role in future GC treatment strategies." (PMID 27867537, 2016). "On the one hand, the upregulation of the expression of AQP3 and AQP5 in the stomach indicates their important roles in the development of gastritis and gastric cancers." (PMID 27589719, 2016). "AQP3 serves a key role in the progression and metastasis of various types of cancer: AQP3 can upregulate matrix metalloproteinases (MMP1, MMP2 and MMP9) and induce EMT by activating the PI3K/AKT signaling in gastric cancer." (PMID 39611488, 2025). "Loss of AQP3 might lead to reduced expression of inflammatory factors like IL-6 and TNF-α, and AQP3 inhibition could decrease the production of IL-6, IL-1β, and TNF-α, impairing intestinal bacteria clearance and contributing to gastric cancer progression." (PMID 39060229, 2024). "AQP3 and AQP5 ensure significant functions in gastric cancer." (PMID 37681902, 2023). "Moreover, AQP3 promotes the expression of CD44, a cancer stem marker, through the Wnt/β-catenin signaling pathway in gastric cancer cells." (PMID 35252273, 2022). "Similarly, in human gastric carcinoma cells, upregulated AQP3 levels correlated with increased MMP2 and MMP9 expression, whereas AQP3 silencing reduced MMP2 and MMP9 expression." (PMID 35163313, 2022). "Intriguingly, AQP3 mRNA expression was associated with better OS with positive and negative HER2 in gastric cancer patients, whereas AQP9 and AQP10 mRNA levels were associated with better OS with negative HER2." (PMID 29678898, 2018). "In gastric cancer, EGF-induced AQP3 upregulation enhances the mesenchymal transformation." (PMID 29922644, 2018). "Research on the effects of curcumin in other cancers such as gastric cancer, in which EGF-induced AQP3 up-regulation occurs, might further understanding of the role of AQP3 in cell migration and invasion." (PMID 29922644, 2018). "Similarly, in a study using the gastric cancer cell lines SGC7901 and MGC803, overexpression of AQP3 correlated with down-regulation of E-cadherin expression and up-regulation of vimentin and fibronectin expression." (PMID 28991174, 2017). "For example, the mRNAs of AQP1, AQP3, AQP4, AQP5 and AQP11 are also found in human gastric cancers." (PMID 27589719, 2016). "Additionally, we investigated the effect of AQP3 on CD44 expression and stem-like properties of gastric cancer cells and elucidated the mechanism involved in this effect." (PMID 26918728, 2016). "In the present study, we found that H. pylori infection upregulated AQP3 expression in non-cancerous mucosa and gastric cancer tissues." (PMID 23152856, 2012). "AQP3 protein expression in gastric cancer tissues was higher than in corresponding normal tissues, although weak to moderate positive AQP3 reactivity was found in the non-cancerous mucosa." (PMID 23152856, 2012).
gastric cancer (continued). "Moreover, when AQP3 protein levels were decreased by knockdown, gastric cancer SGC7901 and MGC803 cells formed fewer spheroids, indicating that AQP3 promotes spheroid formation of these cells and AQP3 knockdown in pancreatic BXPC3 and HPAFII cancer cells, decreased cell proliferation." (PMID 28991174, 2017). "However, the relationships of AQP3 with GIM classification and with other proteins, and their roles in the transition from GIM to gastric carcinoma (GC) remain unknown." (PMID 28968998, 2017). "Similarly, another study pointed out that c-Met could regulate the AQP3 expression via the ERK signal pathway in human gastric carcinoma, which affected the metastasis and invasion of human gastric carcinoma." (PMID 27589719, 2016). "In addition, AQP3, AQP4 and AQP5 exhibited differential expression between human gastric carcinomas and corresponding normal tissues; AQP3 and AQP5 protein expression was detected as remarkably stronger in the human carcinoma tissues than that in normal mucosa by immunofluorescence." (PMID 27589719, 2016). "However, whether AQP3 is involved in H. pylori infection-related gastric cancer is unknown, and no studies of which we are aware have investigated alterations in the expression of AQP3 in H. pylori-infected stomach mucosa." (PMID 23152856, 2012). "In addition, we showed that AQP3 promotes the migration and proliferation of human gastric carcinoma AGS and SGC7901 cells, suggesting that AQP3 may be a potentially important determinant of tumor growth and the spread of human gastric carcinoma." (PMID 23152856, 2012).
breast carcinoma (52 papers, 2008 to 2025). "In human breast cancer cell lines, AQP3 peroxiporin activity was found to be implicated in CXCL12/CXCR4-dependent breast cancer cell migration." (PMID 39941100, 2025). "In particular, AQP3 has been mostly associated with cancer progression and metastasis and is suggested to have high potential as a therapeutic target for breast cancer." (PMID 37175840, 2023). "In HER2+ early breast cancer, AQP3 overexpression was associated with poor prognosis and poor recurrence-free survival." (PMID 36212456, 2022). "Estrogen receptor positive (ER+) breast cancer tissues with high AQP3 expression were associated with poorer cell differentiation and increased lymph node metastasis." (PMID 36212456, 2022). "In T47D breast cancer cells, overexpression of AQP3 caused decreased protein levels of E-cadherin, while Snail expression was increased." (PMID 28991174, 2017). "The AQP3 gene has an estrogen-responsive component and increases its expression in response to estrogen stimuli, implying an association between AQP3 and estrogen receptor positive breast cancer." (PMID 38336645, 2024). "On the other hand, the mechanisms underlying AQP3 upregulation in breast cancer also remain unclear." (PMID 26219409, 2015). "On the other hand, we found that higher AQP3 levels were associated with poorer cell differentiation and more lymph node metastasis in ER-positive breast cancer patients, suggesting that AQP3 may be an enhancer in breast cancer progression." (PMID 26219409, 2015). "However, it should be questioned whether AQP3 can act as a breast cancer-specific diagnostic biomarker or therapeutic target." (PMID 25886458, 2015). "Extracellular H2O2 produced by the CXCL12-activated membrane NADPH oxidase 2 (NOX2) is taken up by breast cancer cells through AQP3 with consequent activation of H2O2-mediated signaling pathways and stimulation of cancer cell migration." (PMID 39941100, 2025). "According to the literature, AQP3 seems to be more associated with FGFR-PI3K and FGFR-ERK signaling pathways, being required for FGF-2-induced cell migration in human breast cancer cells and, thus, influencing cancer metastasis." (PMID 40305202, 2025). "AQP3 also promotes cell migration and infiltration in oestrogen receptor positive breast cancer by affecting the expression of markers involved in epithelial mesenchymal transition (EMT) and actin-cytoskeleton rearrangement." (PMID 38336645, 2024). "In the initial phases of breast cancer, AQP3 expression is increased through the FGFR-PI3K or FGFR-ERK signaling pathways in reaction to fibroblast growth factor, as well as estrogen." (PMID 38336645, 2024). "In cell cultures, AQP3 expression was linked to enhanced metastasis of T47D, MDA-MB-231, and DU4475 breast cancer cells, but AQP3 silencing drastically decreased metastasis in comparison with normal cells." (PMID 38336645, 2024). "AQP3 appears to be involved in the modulation of PI3K/AKT in breast cancer cells, and a similar condition in sperm cells should not be ruled out." (PMID 39596043, 2024). "In breast cancer cells, AQP3 is associated with the induction of CXCL12/CXCR4-dependent cell migration, a critical process in breast cancer progression and metastasis." (PMID 39125952, 2024). "AQP3 expression in breast cancer cells was boosted by the addition of 5′-deoxy-5-fluoropyrimidine nucleosides (5′-DFUR), which was utilised in the chemotherapy of solid tumours." (PMID 38336645, 2024). "AQP3-mediated modulation of the PI3K/AKT signaling pathway is specific to different breast cancer cell types." (PMID 38136293, 2023). "FGFR/PI3K and FGFR/ERK signaling pathways play a crucial roles in FGF-2-induced AQP3 expression and contribute to cell migration and metastasis in breast cancer." (PMID 38136293, 2023). "In order to confirm the presence of AQP3 in the breast cancer cell lines, we performed screening for several aquaporin isoforms." (PMID 37175840, 2023).
breast carcinoma (continued). "The AQP3/SCAF11/FOXO1 axis was identified as the mechanism by which CAP targets breast cancer stemness." (PMID 38136293, 2023). "Several aquaporins are overexpressed in breast cancer, and AQP1, AQP3 and AQP5 have been linked to spread to lymph nodes and poor prognosis." (PMID 37681917, 2023). "AQP3 expression also correlates with tumor progression and malignancy and is, therefore, a potential target in breast cancer therapy." (PMID 37175840, 2023). "Meanwhile, AQP3 also participates in the cytotoxic effect exerted by nucleoside-derived drugs, including 5-fluorouracil and gemcitabine, in breast cancer and colon cancer." (PMID 35972604, 2022). "The expression patterns of AQP3 in thyroid cancer, breast cancer, and prostate cancer are exceptional." (PMID 35972604, 2022). "Breast cancer cells and prostate cancer cells treated with AQP3-siRNA were more sensitive to cryoinjury than control-siRNA." (PMID 35972604, 2022). "Additional studies in MDA-MB-231 and DU4475 breast cancer cells found AQP3 to be critical for cell migration through cell signaling." (PMID 36212456, 2022). "Steroid hormonal control of expression is illustrated by the upregulation of AQP3 by estrogen, acting at an estrogen-responsive element in the aqp3 promoter, relevant to increased motility in estrogen-receptor-positive breast cancers." (PMID 35163313, 2022). "Even more, C-X-C motif chemokine ligand 12 (CXCL12) stimulates H2O2 transport across the membrane by AQP3 in breast cancer cells MDA-MB-231 and DU4475." (PMID 33947079, 2021). "Studies confirmed that AQP3 overexpression increased cell migration and invasion for oestrogen-receptor positive breast cancer cells, as well as for keratinocytes." (PMID 33947079, 2021). "In contrast, an analysis of biopsy samples from HER2-positive early breast cancer patients showed that high levels of AQP3 protein correlated with longer periods of disease-free survival, pointing to a protective influence in vivo." (PMID 33499000, 2021). "AQP3 was shown to be located in the nucleus, cytoplasm and membrane of ER-silenced breast cancer cells and shown to be translocated from the nucleus into newly formed blebs." (PMID 33917751, 2021). "One study showed that in the MDA-MB-231 breast cancer cell line CXCL12 stimulation leads to an increased localization of AQP3 at the leading edge of the cell." (PMID 34099798, 2021). "Soon, evidence of AQP3 overexpression in several other types of cancers, including breast cancer, accumulated." (PMID 33947079, 2021). "In parallel, it was shown that the AQP3 gene has an oestrogen-response element and responds to oestrogen stimuli by increasing its expression suggesting a link between AQP3 and oestrogen receptor positive breast cancer." (PMID 33947079, 2021). "Estrogen receptor (ER)-positive breast cancer cells have been shown to have higher AQP3 expression than ER-negative cells." (PMID 33917751, 2021). "Both increased and decreased levels of AQP3 expression have been suggested to have beneficial effects in breast cancer." (PMID 33499000, 2021). "For example, AQP1 is overexpressed in breast cancer and colorectal cancer, whereas AQP3 is upregulated in prostate and breast cancers." (PMID 33499000, 2021). "AQP3 is upregulated in the early stages of breast cancer, in response to fibroblast growth factor via FGFR–PI3K or FGFR–ERK signaling pathways, and estrogen." (PMID 32679804, 2020). "Recent evidence showed a novel role for AQP3-mediated H2O2 transport in the mechanism of breast cancer cell migration." (PMID 31277235, 2019). "In these cells, H2O2 was produced in the extracellular space via Nox2 in response to CXCL12 stimulation, then rapidly transported into breast cancer cells through AQP3." (PMID 30893772, 2019). "AQP3 also serves to encourage cell migration and invasion in estrogen receptor positive breast cancer by influencing expression of molecules critical to epithelial mesenchymal transition (EMT) and reorganization of the actin-cytoskeleton." (PMID 30555637, 2018).